FST (follistatin)
Diseases named in the same sentence as FST in open-access papers (continued):
Sharing a sentence is not in itself a finding about the gene and the disease.
tumor (74 papers, 2007 to 2026). "For instance, higher serum FST levels correlate with bone metastasis in prostate cancer and are associated with larger tumor sizes and a poorer prognosis in patients with hepatocellular carcinoma." (PMID 38392348, 2024). "We propose FST as a prognostic biomarker for patient survival and a compelling candidate mediating the broad effects of p63 on the tumor and its associated microenvironment." (PMID 37492374, 2023). "We show through loss- and gain-of-function studies that FST predominantly imparts a tumor-growth and migratory phenotype in HNSCC cells." (PMID 37492374, 2023). "The angiogenic factors HGF and follistatin were associated with poor prognosis in esophageal cancer patients when measured in the post-(chemo)therapeutic tumor tissue." (PMID 32023907, 2020). "Hepatocyte Growth Factor (HGF) and Follistatin in the tumor tissue were associated with patient survival." (PMID 25885021, 2015). "Angiogenic factors were associated with the following clinicopathological factors: tumor tissue expression of Angiopoietin-2 and Follistatin was higher in SCC compared to AEG (p = 0.022 and p = 0.001)." (PMID 25885021, 2015). "Angiopoietin-2 and Follistatin protein levels within the tumor tissue were associated with tumor type (p = 0.022 and p = 0.001)." (PMID 25885021, 2015). "High HGF and Follistatin expression in the tumor tissue was associated with poor prognosis in all patients (p = 0.037 and p = 0.036)." (PMID 25885021, 2015). "Using the median as cut-off, high HGF and Follistatin expression in the tumor tissue were associated with poor patients’ prognosis." (PMID 25885021, 2015). "Serum FST is also associated with tumor stage in lung and advanced colorectal cancers." (PMID 38392348, 2024). "The results revealed that the upregulation of ANGPTL4 and Follistatin were significantly and positively associated with the extent of tumor regression, indicating that these proteins may serve as functional biomarkers linking propranolol exposure to therapeutic response." (PMID 41487524, 2025). "In addition, we investigated whether TETs express Activin A or Follistatin, and whether there is an association between Activin A and Follistatin with tumor microvessel density (MVD) and outcome." (PMID 31757999, 2019). "In addition, mechanical stimulation is sufficient to counteract the adverse tumor-induced effects on muscle cells, in association with an increased follistatin/activin ratio in the cell culture medium, indicating that myotubes actively release follistatin upon stretching." (PMID 31068826, 2019). "We found a notable enrichment of FST within TP63-expressing tumor epithelial cells driven by the activation of the MAPK signaling pathway." (PMID 38392348, 2024). "The Wilms’s tumor gene Wt1, which activates Fst (follistatin) during follicle development, was also downregulated in F1–D1 ovaries." (PMID 36982971, 2023). "Future research efforts will involve a systematic and tumor subtype-specific approach to evaluating the role of FST in HNSCC." (PMID 37492374, 2023). "In both analyses, all genes except CSF3 and FST were differentially expressed between the tumour and tumour-adjacent tissue." (PMID 37509322, 2023). "High follistatin levels were observed in TC patients and were related to tumor microvessel density and advanced tumor stage." (PMID 38069386, 2023). "Determination of the role of FST in regulating longer term biological endpoints, such as proliferation, as well as tumour growth in vivo, necessitated generation of stable FST knockdown cell lines by CRISPRi." (PMID 36608258, 2023). "Upregulated genes included cartilage-associated genes (COMP, MATN3, and COL11A2), collagen- and extracellular matrix-associated genes (COL9A2, SFRP2, and SERPINE2), and tumor metastasis- and progression-associated genes (SLC38A3, FST, ITGA11, and DGKI)." (PMID 36192442, 2022).
tumor (continued). "Co-injection of human PSCs enhanced tumorigenicity significantly, while neutralization of activin A with anti-activin A antibody or follistatin significantly decreased tumor growth only in cases where PSCs were also injected." (PMID 35618735, 2022). "Follistatin over-expressing hUC-MSC attenuated metastatic tumor growth and tumor nodule number in the lung." (PMID 35955703, 2022). "In this paper, we identified that down-regulation of FST confers poor prognosis in patients with TNBC and down-regulation of FST expression inclines to reflect tumor growth of TNBC." (PMID 34001106, 2021). "This study measured activins and follistatin in malignant colon tissues and the results were compared between the early and late clinical stages of cancer according to tumour sidedness and Smad4 expression." (PMID 34867090, 2021). "Follistatin levels were highest in patients with TCs and advanced tumor stage, and significantly correlated with tumor MVD." (PMID 33915954, 2021). "Activine A is a member of the TGFβ superfamily that activates SMAD proteins and gene transcription, while Follistatin antagonizes and degrades Activine A. By the inhibition of Activine A, Follistatin promotes cell proliferation, tumor growth, and angiogenesis." (PMID 33915954, 2021). "Here, levels of HGF and Follistatin differed between the tumor tissue when originating either from EAC or from ESCC." (PMID 32023907, 2020). "We found that BMP7 inhibition via follistatin decreased tumor growth and extended survival compared with anti-PD1 therapy only." (PMID 32973129, 2020). "Preoperative Follistatin serum concentrations decreased significantly after complete tumor resection (505.9 ± 564.9 pg/mL vs. 210.4 ± 280.4 pg/mL; p = 0.014)." (PMID 31757999, 2019). "We calculated Youden-Indices to find optimal cut-off values for Activin A and Follistatin for predicting tumor recurrence." (PMID 31757999, 2019). "To assess the contribution of myokines and putative tumor-derived factors on myotube size and myoblast recruitment, we measured both activin and follistatin levels in the 6d culture media." (PMID 31068826, 2019). "After radical tumor resection postoperative Follistatin serum concentrations reached physiologic serum levels, similar to those found in healthy volunteers (210.4 ± 280.4 pg/mL vs. 254.4 ± 164.5 pg/mL; p = 0.465)." (PMID 31757999, 2019). "Follistatin serum concentrations correlated significantly with tumor stage and decreased to physiologic values after complete tumor resection." (PMID 31757999, 2019). "Follistatin serum concentrations decreased significantly after radical tumor resection, indicating that Follistatin serum levels are at least partially related to the presence of malignant thymic epithelial cells." (PMID 31757999, 2019). "Herein we investigated for the first time the role of Activin A and Follistatin serum concentrations and tumor expression in TETs." (PMID 31757999, 2019). "Membranous Activin A expression was detected in all tumor tissues of TETs, while Follistatin staining was found in tumor nuclei and cytoplasm." (PMID 31757999, 2019). "Recombinant follistatin counteracts tumor effects on myotubes exclusively by rescuing fusion index, suggesting that it is only partially responsible for the stretch-mediated rescue." (PMID 31068826, 2019). "The resultant females were palpated weekly for tumor formation, and FST overexpression in the tumor epithelium was confirmed by qPCR and IHC." (PMID 28583174, 2017). "Neu/FST bitransgenic tumors also showed no overt differences in morphology compared with single transgenic Neu tumors, despite abundant FST protein expression throughout the tumor epithelium." (PMID 28583174, 2017). "Breast tumour cells can impair activin signaling with evidence that follistatin, secreted by tumour cells, promotes tumour growth and inhibin A promotes stomal invasion and metastasis." (PMID 27761376, 2016).
tumor (continued). "Activin is a tumour suppressor that is bound to a single chain glycosylated peptide, follistatin, from which it must be cleaved to allow receptor ligand interaction." (PMID 27761376, 2016). "Other proposed mechanisms for the development of resistance by tumour cells to the growth inhibitory effects of activin-A include up-regulation of follistatin." (PMID 27835986, 2016). "This review focuses on how the ovarian endocrine hormone, inhibin, interacts with the paracrine factors activin and follistatin, abundant in the primary tumour and bone microenvironment, with subsequent effects on tumour cell survival." (PMID 27761376, 2016). "We found that in the tumor tissue Follistatin and Angiopoietin-2 are differentially expressed between the two tumor types with significantly higher median tissue levels of the two angiogenic factors in SCC patients when compared to AEG patients." (PMID 25885021, 2015). "We found that both activin A and follistatin were secreted from ER-ve and ER + ve cells, but at different levels, hence generating different effects on tumour cell proliferation." (PMID 25884855, 2015). "Recently, several reports have shown that FST is also involved in tumor progression processes including angiogenesis, metastasis and cell apoptosis." (PMID 25159612, 2014). "Follistatin was significantly upregulated in tumor stroma, as compared to tumor cells (p < 0.001) while G-CSF, HGF and MMP-2 showed a trend for an increased expression in the stromal compartment." (PMID 25483099, 2014). "Conversely, FST act as a regulator by binding to Activin and antagonizing its tumor promoting function, specifically cell proliferation." (PMID 22685544, 2012). "FST is also shown to regulate tumor progression, angiogenesis, metastasis and apoptosis, and acts as an antagonist to activin function." (PMID 22685544, 2012). "Although there was no single tumor marker, we identified a set of genes (Bone Morphogenetic Protein inhibitors GPC3, GREM1, FSTL3, and FST) in which at least one gene was over-expressed in 100% of the tumor samples." (PMID 23667740, 2012). "At least one of the inhibitors GPC3, GREM1, FSTL3, and/or FST were over-expressed (FC > 1.5) in 100% of tumor samples." (PMID 23667740, 2012). "The addition of a blocking antibody to follistatin in co-cultures increased the tumor proliferation, indicating that follistatin is involved in the inhibition of tumor proliferation." (PMID 19558675, 2009). "Additionally, in a mouse model, Krneta and co-workers (2006) showed that although FST-expressing R30C tumors displayed increased angiogenesis, they were highly susceptible to undergo serum starvation-induced apoptosis, suggesting a role for FST in limiting tumor progression." (PMID 19740438, 2009). "Follistatin is a good candidate for the tumor inhibition observed by the embryonic progenitor cell lines HiB5 and ST14A." (PMID 19558675, 2009). "Tumor stroma as well as some infiltrating microglia/macrophage-like cells were found to be follistatin positive." (PMID 19558675, 2009). "We further showed that follistatin secretion from the NPC has the potential to decrease tumor proliferation." (PMID 19558675, 2009). "Blocking follistatin secretion from HiB5/ST14A in tumor co-cultures resulted in an increased proliferation rate of the tumor cells." (PMID 19558675, 2009). "The aberrant expression of FST by solid tumors is a well-documented observation, yet how FST influences tumor progression and therapy response remains unclear." (PMID 38392348, 2024). "Collectively, the evidence surrounding FST in lung, ovarian, and HNSCC underscores the role of FST as an intermediary between tumor epithelial cells and the stroma, where it facilitates the aggressiveness of cancer cells, likely by fostering an immune-cold and drug-resistant TME." (PMID 38392348, 2024).
tumor (continued). "Furthermore, the source of this increased FST is believed to originate from solid tumors, with transcriptomic studies revealing elevated expression of FST in tumor tissues." (PMID 38392348, 2024). "Notably, dysregulated FST in cancer cells has emerged as a critical factor in promoting tumor growth, an immunosuppressive TME, and, importantly, resistance to commonly utilized cancer drugs." (PMID 38392348, 2024). "Given that FST is enriched within the invasive tumor front within cells that exhibit this partial EMT phenotype, FST likely plays a role in communicating metastatic signals, evading immune detection, and driving a cell survival program that limits therapeutic efficacy." (PMID 38392348, 2024). "As increased copy number aberrations often correlate with increased activity of the amplified gene, we posited that the amplification of EGFR and TP63 in HNSCC may explain the upregulation of FST within tumor epithelial cells." (PMID 38392348, 2024). "Importantly, the serum concentration of Follistatin correlates significantly with tumor staging and microvessel density (MVD), reverting to physiologically balanced levels upon complete tumor resection." (PMID 37849766, 2023). "Our analysis thus far has focused on the expression of FST by epithelial cells; however, FST could also be expressed by the myriad cell types that make up the tumor microenvironment." (PMID 37492374, 2023). "Similarly, the disruption of functional follistatin can affect the proliferation of tumor cells and plays an essential role in the progression of malignant diseases." (PMID 37243119, 2023). "In addition, treatment with follistatin, an antagonist of activin A, significantly reduced the tumor volume in an orthotopic mouse model in vivo." (PMID 36650150, 2023). "Follistatin secretion from NPCs decreases tumor growth and can even inhibit tumor growth in vitro." (PMID 35359410, 2022). "Importantly, FST overexpression significantly suppressed tumor growth and also reduced the expression of mDia2 in the stroma." (PMID 32150356, 2020). "Follistatin could prevent Activin A induced growth inhibition and apoptosis and therefore Follistatin fosters cell proliferation and tumor growth." (PMID 31757999, 2019). "Altogether, these data suggest an adverse effect on myotubes of tumor cell- and muscle-derived activin, which could be counteracted by the mechanically stimulated secretion of follistatin by myotubes." (PMID 31068826, 2019). "It was the primary aim of the study to evaluate whether serum Activin A and Follistatin serum concentrations correspond to histologic tumor subtype, stage and tumor behavior." (PMID 31757999, 2019). "Conversely, Follistatin staining was found in tumor nuclei and cytoplasm (p = 1.000)." (PMID 31757999, 2019). "Worth noting, the CM and the DC have opposite, significant effects on follistatin expression, indicating that the exposure to tumor-derived factors, including activin, downregulates follistatin production in muscle cells, while the mechanical stimulation rescues follistatin expression and release." (PMID 31068826, 2019). "Further study of Follistatin and Activin A in TETs is warranted as the molecules may serve as targets to inhibit tumor angiogenesis and tumor progression." (PMID 31757999, 2019). "Follistatin serum levels were highest in patients with TCs and advanced tumor stage." (PMID 31757999, 2019). "Follistatin has been show to suppress tumor growth by inducing cancer cell apoptosis." (PMID 27270319, 2016). "Furthermore the addition of ZOL to chemotherapy reduced serum follistatin levels at day 5 post treatment specifically in patients with ER-ve tumours compared to patients receiving chemotherapy alone." (PMID 25884855, 2015).
tumor (continued). "In order to validate that ZOL induces changes in follistatin and pSmad2L in ER-ve tumours in vivo, ER-ve MDA-MB-436 sub-cutaneous tumour sections from mice treated with or without ZOL (100 μg/kg, weekly for 6 weeks, equivalent to the 4 mg clinical dose) were evaluated." (PMID 25884855, 2015). "We hypothesise that the biological activity of activin A depends on the ratio of activin A to follistatin in the tumour microenvironment." (PMID 25884855, 2015). "Since the increased resistance of cancer cells to glucose deficiency contributes positively to tumor progression, out data suggested that AUF1 might inhibit solid tumor development via destabilization of FST mRNA." (PMID 25159612, 2014). "The production of follistatin by NPCs resulting in tumor-growth inhibition could be mediated by many different mechanisms in vivo e.g. inhibition of immuno-suppression, dysregulation of matrix production or direct anti-proliferative effects on the tumor." (PMID 19558675, 2009). "In addition, there were distinct sub-populations of tumor cells within the tumor bulk, which were follistatin positive." (PMID 19558675, 2009). "Given the convergence of p63 and FST expression in the basal resident stem and progenitor cell compartment of the epithelium, it is likely that the roles of these two molecules may be intertwined, not only in normal biology, but in tumor biology as well." (PMID 38392348, 2024). "Further investigations are needed to elucidate the functional role of FST in tumor biology and whether it presents a candidate target for small-molecule inhibition or is itself a molecule to enhance therapeutic response, ultimately improving health outcomes for cancer patients." (PMID 38392348, 2024). "Furthermore, analysis of single-cell RNA sequencing data from HNSCC patients unveiled cancer cells as the dominant source of FST within the tumor microenvironment and exposed a correlation between the expression of FST and its regulators with immune infiltrates." (PMID 37492374, 2023). "To test whether activin A plays a role in fibroblast-promoted tumorigenesis in vivo, we injected anti-activin A antibody or follistatin (an activin antagonist) every three days for a total of four injections into NOD/SCID/IL2Rγnull (NSG) mice xenografted with BxPC-3 tumor cells and human PSCs." (PMID 35618735, 2022). "Interestingly, when we measured the amount of αSMA+ cells after neutralization with anti-activin A antibody or treatment with follistatin in tumor xenografts co-injected with PSCs in mice, we found that the number of αSMA+ cells adjacent to the tumor was significantly reduced in these mice." (PMID 35618735, 2022). "Moreover, high follistatin levels in the tumor tissue were significantly associated with positive lymph nodes and distant metastasis." (PMID 32023907, 2020). "Therefore, the amount and characteristic pattern of tumor vessels in TETs most likely depend on proliferation of endothelial cells, which might be influenced by Follistatin." (PMID 31757999, 2019). "Hence, manipulation of the Activin A and Follistatin system in TETs may represent a potential target to interfere with tumor angiogenesis, tumor growth and metastases in TETs." (PMID 31757999, 2019). "Hence, manipulation of the Activin A and Follistatin system in TETs may represent a potential target to interfere with tumor angiogenesis and tumor progression in TETs." (PMID 31757999, 2019). "Additionally, some studies support the role of FST in controlling tumor metastasis." (PMID 30377409, 2018). "FST may have a tumour-suppressor role via the inhibition of BMP2 activity." (PMID 28878391, 2017). "Angiogenin may bind with follistatin, another angiogenic protein that in an in vivo model was found to increase the number of tumor associated capillaries but not tumor size." (PMID 21609465, 2011). "Promoter hypomethylation in tumor tissues correlated with overexpression of LAMC2, CTHRC1, CXCL13, FST, SPP1, and PLAU, whereas CDKN2A showed hypermethylation." (PMID 41776121, 2026).